SOD2 (superoxide dismutase 2)
Diseases named in the same sentence as SOD2 in open-access papers (continued):
Sharing a sentence is not in itself a finding about the gene and the disease.
leprosy (5 papers, 2013 to 2021). Leprosy is a chronic infectious disease affecting primarily the skin and peripheral nervous system. "Recently, in a human population study, a genetic variant leading to reduced activity of Sod2 was found to be associated with increased resistance to leprosy, a disease caused by Mycobacterium leprae." (PMID 29208761, 2018). "Once again, it is interesting to note that SOD2 was also suggested to participate in leprosy susceptibility through a genomic scan." (PMID 23798993, 2013). "Our finding of low levels of SOD2 gene expression in skin samples of elderly L-Lep patients is interesting, considering that variants of this gene are located at the same genomic locus as PRKN, a well-known leprosy susceptibility gene." (PMID 33690671, 2021). "Samples from leprosy patients showed down-regulation of CCL2, CCL3, CCL4 (p<0.05), while IL1β and SOD2 were borderline significant (p<0.1), confirming a repression of these genes by M. leprae ex vivo, as was observed in vitro in THP-1." (PMID 23798993, 2013).
male infertility (5 papers, 2015 to 2024). The inability of the male to effect fertilization of an ovum after a specified period of unprotected intercourse. "When multiple antioxidant gene variations were analyzed, the PON1 Arg192Glu (rs662) and SOD2 Val16Ala (rs4880) variants were associated with a significantly higher risk of male infertility and levels of sperm DNA fragmentation and 8-OHdG." (PMID 26618172, 2015). "In a Chinese population, the SOD2 Val16Ala (rs4880) variant is associated with a significantly higher risk for male infertility, higher levels of sperm DNA fragmentation and 8-OHdG, and a low level of SOD activity." (PMID 26618172, 2015). "This study offers mitochondrial pathology as the underlying etiology of idiopathic male infertility and suggests an association with the downregulated expression of mitochondrial PRDX5 and SOD2." (PMID 39726694, 2024). "Visualization of this complex environmental health dataset illuminates candidate genes (BAX, BCL2, and SOD2) and phenotypes (male gonad development, apoptosis, and spermatogenesis) connecting the chemicals to male infertility, and thus may represent critical intermediate molecular mechanisms." (PMID 39104826, 2024). "In our proteomics analysis, SOD2 and PRDX5 were underexpressed, while GSR was overexpressed, underscoring their potential significance in the pathophysiology of male infertility." (PMID 39726694, 2024). "Specifically, three mitochondrial proteins (GSR, PRDX5, and SOD2) exhibited expression patterns that have not been previously documented in the context of male infertility." (PMID 39726694, 2024).
malignant mesothelioma (5 papers, 1998 to 2024). A malignant neoplasm of the pleura or peritoneum, arising from mesothelial cells. "Asbestos is also responsible for inducing an increase in the expression of antioxidant enzymes, including manganese-containing superoxide dismutase (MnSOD, SOD2), catalase, and heme oxygenase, in both malignant mesothelioma cells and the lungs of rodents." (PMID 38390570, 2024).
membranous nephropathy (5 papers, 2012 to 2024). "High levels of circulating anti-SOD2 antibodies, limiting the detoxyfing activity of SOD2, have been detected in autoimmune Gn(lupus nephritis and membranous nephropathy) in association with persistence of proteinuria and worsening of renal function." (PMID 37176025, 2023). "On the other hand, elevated levels of circulating anti-SOD2 antibodies were recently detected, which limited the detoxifying activity of SOD2 in LN and membranous nephropathy in association with persistent proteinuria, which could favor worsening renal function." (PMID 38136185, 2023). "Circulating and renal deposits of anti-SOD2 antibodies have been detected in patients with membranous nephropathy and lupus nephritis, two main examples of autoimmune disease of the kidney, which correlate with the clinical outcome." (PMID 39765847, 2024). "In this regard, evidence for oxidative stress, the glomerular neoexpression of aldose reductase (AR) and SOD2, and the appearance of anti-AR and anti-SOD2 autoantibodies was recently reported in human membranous nephropathy suggesting that oxidative stress may generate new autoimmune targets." (PMID 22701794, 2012).
migraine (5 papers, 2015 to 2023). "This hypothesis is corroborated by the results obtained in the present study showing an association between specific LTA and SOD1/SOD2 genotypes and the development of focal migraine-related visible WMHs." (PMID 36430258, 2022). "A polymorphism in the SOD2 gene was associated with unilateral cranial autonomic symptoms in migraine with aura patients, and in paediatric migraine patients’ polymorphisms in the SOD2 and catalase gene were significantly higher in both migraine with and without aura patients compared to controls." (PMID 30974836, 2019).
non-alcoholic steatohepatitis (5 papers, 2016 to 2022). "Moreover, SOD2 Ala16Val SNPs also serve as an important risk factor for atherosclerotic burden, cardiac events, and nonalcoholic steatohepatitis." (PMID 26881045, 2016). "A study in the nonalcoholic steatohepatitis model showed that RORα reduced ROS levels in hepatocytes and suppressed hepatic oxidative stress, which is accompanied with induction SOD2 and Gpx1." (PMID 34639006, 2021).
status epilepticus (5 papers, 2019 to 2023). Status epilepticus is defined as a continuous seizure lasting more than 30 min, or two or more seizures without full recovery of consciousness between any of them. "SIRT1 activation following status epilepticus in rats has been shown to enhance PGC1α, superoxide dismutase 2 (SOD2), and uncoupling protein 2 (UCP2)." (PMID 38203294, 2023). "Similarly, in an experimental model of status epilepticus, ALLO treatment induced higher SOD2 expression." (PMID 36674713, 2023).
thyroid cancer (5 papers, 2019 to 2024). "It has been demonstrated that the PIM-1 kinase increases the protein expression of the antioxidants GPX1 and SOD2 in thyroid cancer cells, whereas its inactivation increases ROS." (PMID 35682803, 2022). "Interestingly, the increased expression of GPX1 and SOD2 and augmented GPX and SOD activities have been reported in thyroid cancer when compared with normal tissue." (PMID 35682803, 2022). "The average Log2 median-centered intensity-normalized SOD2 expression in the normal thyroid is markedly lower, −0.34, than that of SOD1 and SOD3 but different from these two because SOD2 expression gradually increases, correlating with the malignancy of thyroid cancer." (PMID 29478325, 2019).
ulcerative colitis (5 papers, 2014 to 2024). An inflammatory bowel disease involving the mucosal surface of the large intestine and rectum. "Single nucleotide polymorphisms (SNPs) in the antioxidant genes SOD2 (rs4880) and GPX1 (rs1050450) were genotyped in a Portuguese population comprising 436 Crohn’s disease and 367 ulcerative colitis patients, and 434 healthy controls." (PMID 28052094, 2017). "Genotypic frequencies and overall association of genetic variants in SOD2 and GPX1 with Crohn’s disease and ulcerative colitis." (PMID 28052094, 2017). "Reactive oxygen species levels are higher in the ulcerative colitis region, but reactive oxygen species scavenging enzyme SOD2 is barely detected in resident macrophages, resulting in distinct reactive oxygen species vulnerability for inflammatory macrophages and resident macrophages." (PMID 37344477, 2023).
age-related hearing loss (4 papers, 2013 to 2025). "In age-related hearing loss models, the DNA methylation inhibitor 5-azacytidine reduces SOD2 methylation, mitigates oxidative stress, and inhibits H2O2-induced cell apoptosis." (PMID 41169987, 2025). "The level of SOD2 acetylation, SOD2 activity and Sirt3 expression, as well as their possible relationships, were also investigated to determine the mechanism of presbycusis in the central auditory system." (PMID 24505357, 2014). "For instance, several antioxidant genes, including SOD2, GST or UCP, have been associated to age-related hearing loss and genetic mouse models deficient for antioxidant genes, including Nrf2, Sod1 or genes regulating the mTOR pathway, show accelerated age-related hearing loss." (PMID 32000019, 2020).
amyloid (4 papers, 2007 to 2020). "We also profiled CSF in the 5xFAD mouse model to validate amyloidosis-induced changes, and found consistent mitochondrial decreases (SOD2, PRDX3, ALDH6A1, ETFB, HADHA, and CYB5R3) in both human and mouse samples." (PMID 32711556, 2020). "Because APP overexpression lowers cellular copper and decreased copper levels exacerbates amyloid pathology, we investigated whether the synergistic interplay between sod2 ablation and Alzheimer pathology in Tg2576 transgenics is reflected by lowered brain metal levels." (PMID 17579710, 2007). "Importantly, since no amyloid plaque deposition was found in young mice, this result indicates that the increase of oxidative stress at this age is Aβ plaque independent but dependent on Sod2 activity." (PMID 22276093, 2012). "Conversely, the dramatically low expression of PGC-1α at 12 months in AD neurons, when we first observe hippocampal amyloid deposits (not shown), is concomitant with the lower levels of SOD1, SOD2 and, particularly, GPX1, compared to WT." (PMID 23374228, 2013).
anemia (4 papers, 2010 to 2025). A reduction in the number of red blood cells, the amount of hemoglobin, and/or the volume of packed red blood cells. "We also evaluated genes associated with mitochondrial function (Abcb7, Alas2, and Sod2), which may possibly explain the anemia phenotype in Sf3b1+/− mice." (PMID 25481243, 2014).
autoimmune disease (4 papers, 2011 to 2022). A disorder resulting from loss of function or tissue destruction of an organ or multiple organs, arising from humoral or cellular immune responses of the individual to their own tissue constituents. "A known single nucleotide polymorphism (SNP) rs4880 on the SOD2 gene, causing a mutation from alanine to valine (Ala16Val) in the primary structure of immature MnSOD, has been associated with several types of cancer and other autoimmune diseases." (PMID 36552556, 2022). "Four DEGs (SOD2, GATA3, PPARG, and MAPK14) were related to various functional categories, including “inflammatory response”, “cell activation”, “autoimmune disease”, and “vascular endothelial cell”." (PMID 34026343, 2021).
bipolar disorder (4 papers, 2020 to 2026). A disorder of the brain that causes unusual shifts in mood, energy, activity levels and the ability to carry out day-to-day tasks. "Sod2 single-nucleotide polymorphisms have been reported to be associated with early-onset bipolar disorder." (PMID 41522609, 2026). "Polymorphisms in superoxide dismutase-2 (SOD2) were suggested to modulate white matter architecture in individuals with Bipolar Disorder (BD)." (PMID 41009999, 2025).
chronic lymphocytic leukemia (4 papers, 2013 to 2025). "In chronic lymphocytic leukemia cells, an imbalance between SOD2, which converts harmful superoxide radicals into H2O2, and catalase, responsible for decomposing H2O2, leads to excessive H2O2 accumulation." (PMID 41009046, 2025).
clear cell renal cell carcinoma (4 papers, 2017 to 2023). "Given that mitochondrial O2•− has been implicated in the activation of HIF-1α, decreased SOD2 expression by HIF-1α was proposed as a positive feedback mechanism for HIF-1α signaling in renal clear cell carcinoma." (PMID 29099803, 2017). "Especially in renal clear cell carcinomas, which show pathological similarities with clear cell ovarian carcinomas, high SOD2 expression reflects better mitochondrial function and ROS resistance, and increased SOD2 expression correlates with poor prognosis." (PMID 30700285, 2019).
congestive heart failure (4 papers, 2014 to 2022). Failure of the heart to pump a sufficient amount of blood to meet the needs of the body tissues, resulting in tissue congestion and edema. "Patients with combined chronic heart failure and diabetes mellitus have worse prognoses associated with elevated ROS overproduction but decreased SOD2/NDUFS1 expression rates compared to patients with chronic heart failure without diabetic history." (PMID 33686350, 2021).
coronary atherosclerosis (4 papers, 2019 to 2025). Atherosclerosis of the coronary vasculature. "Gene polymorphisms: SOD2 rs4880, SOD3 rs2536512 and rs2855262, GPX rs3828599, and GSTT1 (deletion) were evaluated the associations with HTG, low HDL-C, high TG/HDL-C ratio, and severity of coronary atherosclerosis." (PMID 31396447, 2019). "Gene polymorphisms in superoxide dismutase (SOD2 and SOD3), glutathione peroxidase-3 (GPX3), and glutathione S-transferase theta-1 (GSTT1) may enable oxidative stress-related lipid abnormalities and severity of coronary atherosclerosis." (PMID 31396447, 2019).
dementia (4 papers, 2016 to 2025). Loss of intellectual abilities interfering with an individual's social and occupational functions. "Among the 2384 unique gene correlates of Gsto1 expression in hippocampus are 128 genes that share a high co-incidence of literature citations—24 of which are known to be associated with AD or dementia, including well studied candidates Chmp2b, Optn, Dlst, Sod2, and Acat1." (PMID 26829228, 2016). "In AD patients, low efficacy of antioxidant response, possibly involving PGC1α as a regulator and SOD2 as an effector, likely allows the vicious cycle linking Aβ, ROS, and oxidative damage to occur, leading to dementia progression." (PMID 33239403, 2021). "Here, the levels of SOD2 and catalase are changed at 12 months of age in the SAMP8 model of early dementia and were changed to that of a young SAMP8 mouse." (PMID 40811673, 2025).
endometrial cancer (4 papers, 2019 to 2025). Primary or metastatic malignant neoplasm involving the endometrium (mucous membrane that lines the endometrial cavity). "Decreased expression of IGF1 and MYLK, as well as SOD2 overexpression, were observed in endometrial cancer using both mRNA microarrays and RT-qPCR." (PMID 31795319, 2019). "The simultaneous increase in SOD2 and miR-331-3p level may suggest that the regulation of SOD2 activity in endometrial cancer occurs at the translational level." (PMID 31795319, 2019).
head and neck squamous cell carcinoma (4 papers, 2012 to 2025). A squamous cell carcinoma that arises from any of the following anatomic sites: lip and oral cavity, nasal cavity, paranasal sinuses, pharynx, larynx, and salivary glands. "For example, in head and neck squamous cell carcinoma, quiescent Cal27 and FaDu cells exhibited a three- to tenfold increase in SOD2 mRNA compared to proliferating cells." (PMID 40520023, 2025). "In this study, heavy alcohol drinking downregulated ALDH2 gene expression while heavy smoking up-regulated SOD2 gene expression in head and neck squamous cell carcinoma patients (N = 270)." (PMID 28841898, 2017). "Heavy smoking up-regulates SOD2 gene expression level in patients with head and neck squamous cell carcinoma." (PMID 28841898, 2017).
hyperlipidemia (4 papers, 2016 to 2021). "In our studies, hyperlipidemia significantly induced the increase of 4-HNE level in erythrocyte membranes, and it was accompanied by a decrease of SOD2 and SOD3 proteins." (PMID 31089408, 2019).
idiopathic cardiomyopathy (4 papers, 2012 to 2022). A disease of the heart muscle or myocardium proper whose cause is unknown. "Other top-ranked genes include MCL-1 (related to Myeloid Leukemia), ACE2 (related to human coronavirus), SOD2 (related to idiopathic cardiomyopathy, premature aging, sporadic motor neuron disease, and cancer), and so on." (PMID 35571049, 2022).
kidney cancer (4 papers, 2017 to 2021). Primary or metastatic malignant neoplasm involving the kidney. "Therefore, we used ten fresh kidney cancer tissues to perform real-time fluorescent quantitative PCR experiments to detect the correlation between SOD2, CAT, and the macrophage marker CD68." (PMID 34721758, 2021).
malaria (4 papers, 2012 to 2025). Malaria is a serious and sometimes fatal disease caused by a parasite that commonly infects a certain type of mosquito which feeds on humans. "Along with the increase in mROS production, P. vivax infection also triggered an increase in SOD2 expression in all three monocyte subsets from malaria patients." (PMID 34311577, 2021). "Importantly, the mitochondrial enzyme superoxide dismutase 2 (SOD2) is simultaneously induced in monocytes from malaria patients." (PMID 34311577, 2021). "More recently, research in malaria-endemic populations in Cameroon revealed novel loci such as CHST15 and SOD2, with SOD2 demonstrating particularly strong protective effects during the early stages of Plasmodium infection." (PMID 40993672, 2025). "Thus, it is very likely that SOD2 is produced as a negative feedback antioxidative mechanism for preventing tissue damage during malaria." (PMID 34311577, 2021).
metastatic cancer (4 papers, 2019 to 2022). A carcinoma which has spread from the original site of growth to another anatomic site. "The review describes that SOD1 is a known disease-causing gene, whereas the role of SOD2 is less clear, but the general consensus is that overexpression of SOD2 correlates with invasive and metastatic cancer." (PMID 32605023, 2020). "Enhanced expression of SOD2 was associated with cancer metastatic cancer progression." (PMID 36497431, 2022). "Indeed, increased SOD2 expression parallels with glycolytic metabolism, especially in aggressive metastatic cancers, causing the activation of 5′ adenosine monophosphate-activated kinase (AMPK), which further stimulates glycolysis." (PMID 29478325, 2019). "However, SOD2 expression has been shown to increase in late-stage aggressive and metastatic cancers and cell models, indicating the importance of the enzyme for the progression of cancer." (PMID 29478325, 2019).
nasopharyngeal carcinoma (4 papers, 2016 to 2024). A carcinoma arising from the nasopharyngeal epithelium. "Inducing oxidative stress by SOD2 inhibition sensitized nasopharyngeal carcinoma cells to ionizing radiation via ferroptosis induction." (PMID 36737723, 2023). "Mitochondrial superoxide dismutase (SOD2) and manganese-dependent superoxide dismutase (MnSOD) work in the mitochondrial matrix and a recent paper demonstrated that SOD2 can protect mitochondrial membrane lipids from ROS-mediated oxidation in nasopharyngeal carcinoma cells." (PMID 38539832, 2024). "This suggests that sensitizing nasopharyngeal carcinoma cells to ferroptosis using inducers such as erastin, RSL3 or SOD2 inhibitors could be a viable strategy for inhibiting metastasis facilitated by IR." (PMID 36737723, 2023).
oral squamous cell carcinoma (4 papers, 2014 to 2024). "Higher gene expression of SOD2 has been reported in oral squamous cell carcinoma and colorectal adenoma and cancer." (PMID 33821873, 2021). "In this study, we demonstrated that Brucea javanica oil could inhibit the proliferation, invasion and metastasis of oral squamous cell carcinoma by down-regulating MTFR2-mediated aerobic glycolysis and modulating the SOD2/H2O2 signaling pathway." (PMID 39871949, 2024).
sarcoma (4 papers, 2016 to 2021). A usually aggressive malignant neoplasm of the soft tissue or bone. "For example, SOD2 activity is a determinant of radiation therapy efficacy in murine sarcoma." (PMID 33562681, 2021).
tongue cancer (4 papers, 2010 to 2025). A malignant neoplasm affecting the tongue. "SOD2 expression studies in clinical models of tongue cancer have shown a significantly higher expression than in normal tissue samples." (PMID 37108069, 2023).